MED22 (mediator complex subunit 22)
Description:
Component of the Mediator complex, a coactivator involved in the regulated transcription of nearly all RNA polymerase II-dependent genes. Mediator functions as a bridge to convey information from gene-specific regulatory proteins to the basal RNA polymerase II transcription machinery. Mediator is recruited to promoters by direct interactions with regulatory proteins and serves as a scaffold for the assembly of a functional preinitiation complex with RNA polymerase II and the general transcription factors.
Synonyms: Surf-5; SURF5; Med24; SRB6
Tractability: Small molecule: a structure with a bound ligand is known. PROTAC: ubiquitination databases record sites on it; its protein half-life has been measured.
Gene: Protein-coding gene on chromosome 9 (133,338,312 to 133,348,134, reverse strand). Ensembl gene ENSG00000148297.
Subcellular location: Nucleus
Subcellular location (Human Protein Atlas): Nucleoplasm
Pathways (Reactome):
Developmental Biology: Transcriptional regulation of white adipocyte differentiation
Disease: RSV-host interactions
Metabolism: PPARA activates gene expression
Gene Ontology:
Molecular function: protein binding; transcription coregulator activity
Biological process: positive regulation of transcription elongation by RNA polymerase II; positive regulation of transcription initiation by RNA polymerase II; RNA polymerase II preinitiation complex assembly; regulation of transcription by RNA polymerase II
Cellular component: core mediator complex; mediator complex; nucleus; cytoplasm; nucleoplasm
Genetic constraint (gnomAD): Loss-of-function variants: 19 observed, 22.32 expected, observed/expected ratio (o/e) 0.85, 90% interval 0.59 to 1.25. The upper end of that interval is the gene's LOEUF score, 1.25, which puts it in group 5 of 6, group 1 being the genes least tolerant of losing a copy. Missense variants: 165 observed, 194.27 expected, observed/expected ratio (o/e) 0.85, 90% interval 0.75 to 0.97. Synonymous variants: 99 observed, 92.08 expected, observed/expected ratio (o/e) 1.08, 90% interval 0.91 to 1.27.
Homologues: Orthologues: chimpanzee MED22 (99% identical), dog MED22 (96% identical), guinea pig MED22 (96% identical), rat Med22 (96% identical), mouse Med22 (95% identical), pig MED22 (94% identical), tropical clawed frog med22 (70% identical), zebrafish med22 (60% identical), Drosophila melanogaster MED22 (43% identical), Drosophila melanogaster CG32971 (24% identical), Caenorhabditis elegans mdt-22 (23% identical).
Diseases named in the same sentence as MED22 in open-access papers:
MED22 is named in the same sentence as 12 diseases in open-access papers, as found by Europe PMC text mining. Sharing a sentence is not in itself a finding about the gene and the disease. The quoted sentences say what the papers report.
depression (1 paper, 2024). "Of thirteen depression‐associated DRPs, seven proteins including DDC, FGFR2, KIBRA, MED22, OLIG1, RAI1, SLIT2 were upregulated, whereas six proteins including COX3, CRHBP, CSMD1, FSTL1, GRIK4, and LMTK3 were downregulated." (PMID 39373701, 2024). "By contrast, the upregulation of DDC, FGFR2, KIBRA, and MED22, and the downregulation of FSTL1, GRIK4, and LMTK3 in the RagA transgenic mice were negatively correlated with depression." (PMID 39373701, 2024).
glomerular disease (1 paper, 2020). "Moreover, Med22-deficiency in younger mice promoted the progression of glomerular disease, suggesting Med22-mediated processes may have a role in the development of glomerulopathies." (PMID 33208756, 2020). "Vacuole-like structures in podocytes, reminding of the phenotype in our pod-Med22 mice, have been reported in common human glomerulopathies, and therefore, it is possible that Med22 has a role even in human glomerulopathies." (PMID 33208756, 2020). "To see whether haploinsufficiency of Med22 resulted in glomerular diseases, we followed heterozygous mice for up to 15 months." (PMID 33208756, 2020). "Thus, it is difficult to say whether Med22-mediated pathways contribute to the pathogenesis of human glomerular diseases." (PMID 33208756, 2020).
male infertility (1 paper, 2015). The inability of the male to effect fertilization of an ovum after a specified period of unprotected intercourse. "Loss of Med22 function in spermatocytes causes meiosis I maturation arrest male infertility, similar to loss of function of the tMAC subunits or the tTAFs." (PMID 26624996, 2015).
pancreatic tumors (1 paper, 2016). "While differentially expressed subunits in testicular (n = up to 23) and pancreatic tumors (n = 12) were found with a frequency of 100%; only low frequencies for over- (30% in CDK19, n = 121/404) and underexpression (8% in MED22, n = 23/290) were detected in prostate cancer." (PMID 27050271, 2016).
renal failure (1 paper, 2020). "Med22-deficiency in mouse podocytes resulted in renal failure and premature death by 20 weeks of age." (PMID 33208756, 2020).
tumor (1 paper, 2022). "Subsequently, we constructed a risk model based on four LMAGs—LCAT, MED22, MED7, and TXNRD1—which presented noteworthy prognostic values and was closely associated with tumor grade, tumor stage, and T-staging." (PMID 36330335, 2022).
MED22 also shares sentences with these, for which no sentence is quoted: asthma (1 paper); breast carcinoma (1); cyst (1); glomerulopathies (1); prostate carcinoma (1); renal disease (1).